FAM177A1 (family with sequence similarity 177 member A1)
Description:
May act as a negative regulator of the IL-1beta immunogenic cascade.
Synonyms: C14orf24; LOC101927178; NEDWMG
Tractability: PROTAC: ubiquitination databases record sites on it; its protein half-life has been measured.
Gene: Protein-coding gene on chromosome 14 (35,045,117 to 35,116,630, forward strand). Ensembl gene ENSG00000151327.
Subcellular location: Golgi apparatus
Subcellular location (Human Protein Atlas): Vesicles; Nucleoplasm; Predicted to be secreted
Gene Ontology:
Cellular component: Golgi apparatus
Genetic constraint (gnomAD): Loss-of-function variants: 21 observed, 22.91 expected, observed/expected ratio (o/e) 0.92, 90% interval 0.65 to 1.32. The upper end of that interval is the gene's LOEUF score, 1.32, which puts it in group 5 of 6, group 1 being the genes least tolerant of losing a copy. Missense variants: 286 observed, 275.81 expected, observed/expected ratio (o/e) 1.04, 90% interval 0.94 to 1.14. Synonymous variants: 92 observed, 95.37 expected, observed/expected ratio (o/e) 0.96, 90% interval 0.81 to 1.15.
Homologues: Orthologues: macaque FAM177A1 (87% identical), dog FAM177A1 (81% identical), rabbit FAM177A1 (81% identical), mouse Fam177a (76% identical), mouse Fam177a2 (76% identical), guinea pig FAM177A1 (75% identical), pig FAM177A1 (73% identical), rat Fam177a1 (64% identical), zebrafish fam177a1 (50% identical), tropical clawed frog fam177a1 (45% identical), zebrafish FAM177A1 (33% identical), Drosophila melanogaster CG8300 (18% identical). Paralogues in human: FAM177B (23% identical).
Diseases named in the same sentence as FAM177A1 in open-access papers:
FAM177A1 is named in the same sentence as 6 diseases in open-access papers, as found by Europe PMC text mining. Sharing a sentence is not in itself a finding about the gene and the disease. The quoted sentences say what the papers report.
emphysema (1 paper, 2025). "Notably, protein FAM177A1, syntenin-2, and uncharacterized protein C20orf173 explained an additional 0.54%, 0.41%, and 0.38% of the variance in percent emphysema, respectively." (PMID 40616090, 2025).
neurological disorders (1 paper, 2024). "Fam177a1 encodes a protein localized to the Golgi complex and endoplasmic reticulum but of unknown function, and when mutated, is associated with developmental and neurological disorders." (PMID 38307941, 2024).
tumour (1 paper, 2015). "For six of the genes (CCT5, CD72, COL10A1, FAM177A1, SLC25A12 and TDP1), we were unable to identify a correlation (i.e. concordance) between the copy number alteration and gene expression in six of the tumour samples tested." (PMID 25884485, 2015).
FAM177A1 also shares sentences with these, for which no sentence is quoted: breast carcinoma (1 paper); Breast tumor (1); cancer (1).